BRCA1 (BRCA1 DNA repair associated)
Diseases named in the same sentence as BRCA1 in open-access papers (continued):
Sharing a sentence is not in itself a finding about the gene and the disease.
breast cancer (continued). "Our present results identify an inherited form of metabolic reprogramming and provide a conceivable metabolic basis for the rapid cell- and tissue-specific predisposition of breast cancer development associated with BRCA1 haploinsufficiency." (PMID 27259235, 2016). "In our model, WGS correctly identified 132 women (range 121–198) with a pathogenic BRCA1 or BRCA2 mutation who would develop breast cancer." (PMID 27252788, 2016). "Several studies have reported that breast cancer related to BRCA1/2 mutations is often associated with an early age of diagnosis." (PMID 27129401, 2016). "The most recent studies reported an elevated risk for breast cancer in women with BRCA1 mutations if oral contraception was used before the age of 20 years or before the first full term pregnancy." (PMID 27246982, 2016). "Most recently, we and others provided genetic and functional evidence for the critical function of RANK/RANKL in the development of familial BRCA1-mutated breast cancer." (PMID 27881737, 2016). "Other methods of conservative care over high-risk of ovarian and breast cancer patients(BRCA1 or BRCA2 carriers) have proven ineffective." (PMID 26928677, 2016). "Triple-negative breast cancers comprise 15% of breast cancers and are more common in women with BRCA1 mutations." (PMID 28721372, 2016). "Neoadjuvant trials have shown high rates of pCR among BRCA1-associated breast cancers treated with cisplatin." (PMID 27145269, 2016). "Here we present the first 3D comparison of wild type and mutated BRCA1 protein assemblies derived from human breast cancer cells." (PMID 27583302, 2016). "The results showed that certain genotypes of VNTR polymorphisms are associated with the risk of familial breast cancer in BRCA1+ and BRCA2+ carriers." (PMID 27148484, 2016). "For example, an inherited mutation in a BRCA1 gene carries a 65% to 70% lifetime risk of breast cancer; thus, a BRCA1 mutation is classified as a high-penetrance susceptibility gene." (PMID 29225998, 2016). "Five hundred and twenty-three breast cancer patients including 237 diagnosed ≤ 30 years of age and 286 with a family history of breast/ovarian cancer were screened for BRCA1/2 small-range mutations and large genomic rearrangements." (PMID 27553291, 2016). "Patients with germline mutations in BRCA1 have a significant risk of developing breast cancer by age 70, recently estimated at 69% (95% CI 56%-83%)." (PMID 27708239, 2016). "Analysing the largest series of BRCA1 and BRCA2 breast cancers collected to date from both sexes, we have demonstrated that breast tumours arising in BRCA1 and BRCA2 mutation carriers display pathologic differences between males and females." (PMID 26857456, 2016). "We demonstrated that loss of p16 and Brca1 collaboratively induce basal-like mammary tumor development with the induction of EMT." (PMID 27811360, 2016). "For women, the risk of developing breast cancer by age 70 is approximately 60–70% for BRCA1 and 45–55% for BRCA2 mutation carriers." (PMID 27375968, 2016). "It was assessed as a monotherapy in pretreated metastatic BRCA1/2-mutated breast cancer patients: 6/35 (17%) evaluable women experienced response, and median PFS approached to 3.9 months." (PMID 27555886, 2016). "Apart from germ-line BRCA1-mutated breast cancers, a significant proportion of women with sporadic triple negative breast cancer (TNBC) sub-type are known to harbour varying levels of BRCA1-dysfuction." (PMID 27077368, 2016). "RNA and protein analysis of a panel of breast cancer cell lines revealed that BRCA1 deficiency is associated with downregulation of the expression of the pleiotropic tumour suppressor FOXO3." (PMID 27043660, 2016). "The overall breast cancer and ovarian cancer risks for BRCA1 mutation carriers by age 70 years are 50-70% and 40-50%, respectively." (PMID 26967246, 2016).
breast cancer (continued). "BRCA1 germline mutations have been identified in nearly 50% of hereditary breast cancers and 80% of cases with both hereditary breast and ovarian cancers." (PMID 27220670, 2016). "Here, we provide evidence for the targeted anticancer activity of PB against BRCA1 mutated breast cancer cells in vitro as well as in GEMM (Genetically Engineered Mouse Models) of BRCA1 mutated mammary tumor." (PMID 27220670, 2016). "In this single-center observational study, we aimed to investigate the prevalence of both somatic and germline BRCA1/2 variants in unselected Chinese breast cancer patients, and explore their role in tumor phenotype and disease prognosis." (PMID 27257965, 2016). "Here in this study, we also did not observe an increased breast cancer risk associated with the p.G84E mutation in a relatively large study of 3,270 familial non-BRCA1/2 breast cancer cases and 2,327 controls (OR = 0.81, 95% CI = 0.41–1.59, P = 0.54)." (PMID 27424772, 2016). "Methylation at the BRCA1 promoter in blood derived DNA is associated with risk of breast cancer with distinct histological features." (PMID 27902704, 2016). "Among them, BRCA1 was the most frequently mutated gene (17%), and four of the mutations observed in the pCR cohort were associated with hereditary breast cancers in the ClinVar database." (PMID 27959926, 2016). "BRCA1 promoter methylation in blood-derived DNA is associated with a 3.5-fold (95% CI, 1.4–10.5) increased risk for early-onset breast cancer with histological features commonly seen in tumors arising in women with germline BRCA1 mutations." (PMID 27902704, 2016). "Noncarriers of a BRCA1/2 mutation with any first-degree relative with bilateral breast cancer have CBC risk levels similar to those of BRCA1/2 mutation carriers." (PMID 27650678, 2016). "Among patients with TNBC, BRCA1 mutations were identified in 14.4 % of patients with early-onset disease (≤ 30 years), 48.7 % of patients with familial breast cancer and in 80.8 % of patients with familial breast and ovarian cancer." (PMID 27553291, 2016). "In 1993, mutations in breast cancer (BRCA1) gene were suggested to be linked with high incidence of breast cancer in some families." (PMID 27568010, 2016). "Using the retrospective likelihood approach, index SNPs in the three 2p23.2 and 13q22 loci were all associated with BRCA1 breast cancer (rs67073037, P=4.58 × 10−4; rs6562760, P=2.85 × 10−6; rs17181761, P=9.29 × 10−3)." (PMID 27117709, 2016). "Women carrying a BRCA1 mutation have a cumulative risk of 57–65 % of developing breast cancer by 70 years, and those with a BRCA2 mutation have a risk of 45–57 %." (PMID 26748927, 2016). "In previous studies, an increased level of CDH3 has been detected in a small cohort of BRCA1-deficient breast cancer, as well as in nipple aspirate fluid and serum obtained from women with basal-like breast tumors." (PMID 27566577, 2016). "PARP inhibition has also proved to be exquisitely efficient to kill tumour cells deficient in double strand break repair by homologous recombination (HR), such as cells mutated for the breast cancer early onset (BRCA) genes BRCA1 or BRCA2." (PMID 27375368, 2016). "A study from the British population showed that rs1799796 decreases the risk of breast cancer while another study from Belgium reported an increased risk associated with this SNP in BRCA1 and BRCA2 carriers." (PMID 26881229, 2016). "Environmental and lifestyle factors can modify the risk of breast cancer in women with BRCA1/2 mutations." (PMID 26997744, 2016). "Despite the small sample size and detecting only 3 cases with the BRCA1 5382insC mutation, the present and future contribution s of this mutation to the incidence of breast cancer in Uzbekistan can be significant due to the so-called “founder” effect." (PMID 29138730, 2016).
breast cancer (continued). "Here we review the current literature on centromere protein F, its association with breast cancer and present the first case of this antibody being identified in a person with a BRCA1 gene mutation." (PMID 26868636, 2016). "Early age of onset for breast cancer can reflect a genetic predisposition in particular mutations of BRCA1 and BRCA2 genes." (PMID 27770782, 2016). "Two of the 11 BRCA1 mutations were identified in women with high-grade serous ovarian cancer and nine were identified in women with breast cancer." (PMID 26843898, 2016). "Heterozygous germline mutations in breast cancer susceptibility gene 1/2 (BRCA1/2) are responsible for a large fraction of hereditary breast cancers." (PMID 26967246, 2016). "Recently, deleterious mutations in 14 known breast cancer susceptibility genes including BRCA1, BRCA2, and RAD51C were identified at a frequency of 3.7 % in a large series of 1,824 patients with TNBC unselected for family history of breast cancer." (PMID 27553291, 2016). "A major challenge faced by physicians is to identify most appropriate candidates for genetic BRCA1/2 testing since the cost of comprehensive genetic testing can be high and only 3 % of all breast cancers are attributed to BRCA1/2 germline mutations." (PMID 27553291, 2016). "We evaluated the frequency of likely pathogenic or pathogenic BRCA1/2 variants in tumor tissues from 507 Chinese breast cancer patients using next generation sequencing (NGS)." (PMID 27257965, 2016). "The most common genetic marker examined for potential breast cancer cases is the breast cancer susceptibility 1 (BRCA1) and 2 (BRCA2) genes." (PMID 30460281, 2016). "Gene expression analysis of BRCA1-associated breast cancer strongly correlates with the gene expression signature of luminal progenitor cells; BRCA1-mutation carriers in this study appeared to contain an expanded luminal progenitor population." (PMID 27110512, 2016). "In human breast cancer tissues, Slug is frequently overexpressed in BRCA1-mutated and in basal type tumors, and Slug levels correlate with increased metastatic potential and tumor grade." (PMID 26933820, 2016). "Testing options currently include testing only for BRCA1 and 2 mutations, testing for a panel of high-risk breast cancer genes, including BRCA1 and 2, and more extensive panels including moderate risk genes and limited evidence genes." (PMID 26858951, 2016). "CDH3, a plasma membrane protein, is involved in cell adhesion and has been proposed as a tissue marker in human BRCA1-deficient breast cancer as well as a serum marker in basal-like breast cancer." (PMID 27566577, 2016). "Second, loss of BRCA1 function induces a reprogramming of energetic metabolism in breast cancer cells." (PMID 26943589, 2016). "Contradictory results have been obtained from association studies on breast cancer in consanguineous populations for BRCA1 and BRCA2 genes." (PMID 27313952, 2016). "Constitutional DNA methylation of the BRCA1 promoter has been well described and is associated with an increased risk of early-onset breast cancers that have BRCA1-mutation associated histological features." (PMID 27902704, 2016). "BRCA1-mutated simulations had a cumulative incidence of 45.9% (95% confidence interval 44.1–47.7%), a value that falls within the range of five previously published studies on breast cancer incidence in BRCA-1 mutation carriers (17–53%)." (PMID 27023391, 2016). "Another conclusion is that it cannot be excluded that the risk of breast cancer development among constitutional BRCA1 gene mutation carriers subjected to prophylactic surgery varies in a population." (PMID 26928677, 2016). "Breast cancer arising in female BRCA1 mutation carriers is characterized by an aggressive phenotype and early age of onset." (PMID 27566577, 2016). "Strikingly, the majority of breast cancers that arise in BRCA1 mutation carriers manifest molecular phenotypes highly similar to basal-like/triple-negative breast cancers." (PMID 27556296, 2016).
breast cancer (continued). "Among the quite heterogeneous subgroup of TNBC, a subset of predominantly basal-like cancers appears to share molecular characteristics with BRCA1-associated breast cancer, a phenotype recently described as “BRCAness”." (PMID 27756336, 2016). "Loss of DNA repair by BRCA1 functional deficiency in breast cancer has been proposed as a relevant contribution to breast cancer progression for tumors with no germline mutation." (PMID 26979459, 2016). "About 10% of all breast cancers arise from hereditary mutations that increase the risk of breast and ovarian cancers; and about 25% of these are associated with the BRCA1 or BRCA2 genes." (PMID 28009814, 2016). "There were few publications on the influence of breast cancer diagnosis among BRCA1 gene mutation carriers before prophylactic surgery and the incidence of peritoneal cancer in the postoperative period." (PMID 26928677, 2016). "The chosen design aims to provide evidence for a clinically meaningful improvement of carboplatin-olaparib followed by olaparib monotherapy over current standard therapy as first line treatment for BRCA1- or BRCA2-mutated advanced breast cancer." (PMID 27323902, 2016). "About 40-60 % of hereditary breast and ovarian cancers (HBOC) are due to the presence of germline mutations in the breast cancer susceptibility genes type 1 and 2 (BRCA1 and BRCA2)." (PMID 27391110, 2016). "A total of 40 breast cancer patients have been studied for germline mutation in both BRCA1 and BRCA2 genes to contribute to the clarifying of this situation; the entire BRCA1/2 were analyzed using a direct sequencing." (PMID 26997744, 2016). "It has been established that patients with BRCA1 mutations are more likely to develop basal-like breast cancers, including the triple-negative subtype." (PMID 27647460, 2016). "Over 50% of BRCA1 mutation-associated tumours are TN, however, BRCA1 mutations are rarely found in sporadic breast cancer cases and less than 15% of TN tumours harbour BRCA1 mutations." (PMID 27463681, 2016). "Currently, prophylactic mastectomy and/or prophylactic annexectomy are used to decrease breast cancer risk in carriers with BRCA1 mutations; however, there is an urgent need to develop efficient and less aggressive strategies." (PMID 27246982, 2016). "Other factors were shown to disrupt c-Myc binding to hTERT promoter and its transcription activation: Breast cancer 1 (BRCA1) associates with c-Myc via its N-terminal domain and depletes hTERT promoter-bound c-Myc in ovarian, prostate and breast cancer cells." (PMID 27548225, 2016). "All told, 5 % of all breast cancer cases and up to 25 % of familial breast cancer cases can be attributed to high-penetrance mutations in BRCA1 and BRCA2." (PMID 27716388, 2016). "In this work we present the results of our observations in patients with mutation in BRCA1 gene after prophylactic genital tract surgery in relation to development of peritoneal or breast cancers." (PMID 26928677, 2016). "Heterozygous carriers of BRCA1 or BRCA2 mutations have a 82% lifetime risk of breast cancer, as well as 54 and 23% risks of ovarian cancer, respectively." (PMID 27037238, 2016). "Only the ESR1 (rs2046210), TERT (rs2242652) and two 19p13.1 (rs8170; rs56069439) loci had genome-wide significant associations with breast cancer risk for BRCA1 mutation carriers alone." (PMID 27117709, 2016). "Current knowledge of the pathologic characteristics of breast cancers arising in male BRCA1/2 mutation carriers is limited, owing to the small number of carriers included in individual studies." (PMID 26857456, 2016). "This study provided new insights on the complexity of the BRCA1/2 variants in unselected Chinese breast cancer patients." (PMID 27257965, 2016). "While tamoxifen has already shown a protective effect against the risk of breast cancer, including contralateral breast cancer, in populations with BRCA1/2 mutations, the use of tamoxifen as a standard preventive treatment is limited due to its side effects." (PMID 27246982, 2016).
breast cancer (continued). "Breast cancers particularly arising in BRCA1-mutation carriers often exhibit basal-like characteristics, defined by the expression of genes specific to the basal mammary myoepithelial cells." (PMID 27881737, 2016). "TNBC patients account for about 15 % of all breast cancer cases, and about 10-15 % of these harbor germline BRCA1 mutations." (PMID 27590516, 2016). "Approximately 5–10% of female breast cancer are believed to be hereditary, caused by a germline mutation in the BRCA1 or BRCA2 genes." (PMID 27566577, 2016). "Panel testing of 25 cancer susceptibility genes and BRCA1/2 deletion/duplication analysis was performed for 220 Asian breast cancer patients or their family members referred for genetics risk assessment." (PMID 29263802, 2016). "It was also reported that preoperative combined gemcitabine, carboplatin and iniparib is effective for management of early-stage triple-negative and BRCA1/2 mutation-associated breast cancer." (PMID 27147578, 2016). "SNPs in genes involved in the BER pathway have been reported to modify ovarian and breast cancer risk in BRCA1 and BRCA2 mutation carriers." (PMID 27015555, 2016). "Two studies in breast cancer have demonstrated a causal role for HP1α regulating breast cancer progression through BRCA1 functions." (PMID 27385214, 2016). "We chose to use BRCA1/2-related breast carcinomas as an endpoint because both BRCA1/2 mutations confer an increased risk of breast cancer." (PMID 27566577, 2016). "There is only one publication on this subject by Manders in 2011, which reports on an association between increased body weight and an increased risk for breast cancer in BRCA1/2 mutation carriers." (PMID 27473440, 2016). "Neat1 knockdown by two different Neat1 shRNAs significantly impaired the development of Brca1-deficient xenograft mammary tumors." (PMID 27556296, 2016). "Triple negative breast cancer patients have higher rate of BRCA1/2 (Breast Cancer 1/2) mutation and are sensitive to platinum (because of the deficiencies in the DNA repair mechanism)." (PMID 27495967, 2016). "In all, 48 patients had a BRCA1 mutation (15 with breast cancer, 33 with ovarian cancer) and 26 had a mutation within BRCA2 (12 breast, 14 ovary)." (PMID 27002934, 2016). "Increased levels in TOP1 and CDH3 were validated in a large population-based series of breast cancer patients with a BRCA1/2 mutation." (PMID 27566577, 2016). "We characterized a new BRCA1 variant discovered in a breast cancer patient during BRCA1/2 screening by next-generation sequencing." (PMID 28009814, 2016). "We have previously shown that the known human breast cancer genes BRCA1, BRCA2 and ESR1 are associated with CMT in ESS dogs overlapping with this cohort, although not as strongly as the risk factors identified in this GWAS study." (PMID 27158822, 2016). "BRCA1 is a well-known breast cancer tumor suppressor, which is to associate with breast cancer risk and genetic susceptibility." (PMID 27314344, 2016). "The results will provide a reference for the pattern of nursing care among breast cancer patients who have a BRCA1/2 mutation, to develop effective nursing interventions of these patients." (PMID 27428375, 2016). "Platinum agents are highly effective in combating BRCA1-associated breast cancer because there is defect in the homology-directed DNA repair capability of these tumors that contributes to genomic instability." (PMID 27806319, 2016). "In summary, germline or somatic BRCA1/2 P/LP variants were detected in ~10% of the unselected breast cancer patients from a single hospital in West China." (PMID 27257965, 2016).